NRP1 (neuropilin 1)
Diseases named in the same sentence as NRP1 in open-access papers (continued):
Sharing a sentence is not in itself a finding about the gene and the disease.
tumor (continued). "VEGF can directly bind to Neuropilin 1 (Nrp-1) on Tregs and guide their migration into a tumor." (PMID 34149730, 2021). "Additionally, the molecular mechanisms of cancer pathway were chosen to explore the alteration of tumor-related genes following NRP1 knockdown in BC." (PMID 34249735, 2021). "Furthermore, while PLEXIND1 potentially engages SMAD3 and NRP1 to mediate tumor growth in BxPC-3 cells, the involvement of RAC-1 and KRAS is unclear." (PMID 34439202, 2021). "This correlation highlights the possible role of NRP1 in the regulation of tumor immune system." (PMID 34277411, 2021). "NRP1 could promote tumor progression through potentiating the activity of the HGF/SF autocrine c-Met signaling pathway." (PMID 33995640, 2021). "The higher expression of NRP-1 has also been found in TNBC tumor tissues." (PMID 33912463, 2021). "Moreover, they observed a significant reduction in VEGFR signaling and tumor growth by blocking the interaction between NRP-1 and VEGF165 using an NRP-1 antagonist." (PMID 33836774, 2021). "Additionally, VEGF-A can act on VEGFR1 or NRP-1 expressed in the tumor microenvironment of host cells to promote metastasis and immune suppression." (PMID 34302038, 2021). "Because of the interaction with VEGF, NRP1 enhances angiogenesis, including the tumor angiogenesis." (PMID 34168096, 2021). "Analysis with TIMER showed strong correlation between NRP1 expression and the abundance of tumor progression-related genes, MMP1, MMP3, MMP9, VEGFC, FLT4 and CXCL12 in LUSC, while there isn’t clear association between NRP1 expression and this panel of pro-tumorigenic genes in LUAD." (PMID 34168096, 2021). "NUPR1 participates in the regulation of tumor cell autophagy, apoptosis, growth, migration, and invasion; however, no study describing the association with NRP1 has been reported before." (PMID 34249735, 2021). "NRP1 is expressed on human plasmacytoid dendritic cells and may enhance T regulatory cells’ tumor infiltration to promote immunosuppression." (PMID 34298996, 2021). "Although in a lower proportion compared to the tumor vascular network, the basal protein expression of NRP-1 in healthy tissues could have an impact on distribution." (PMID 34885871, 2021). "Further study is required to validate whether this upregulation of NRP-1 is a common phenomenon among tumor cells that survive irradiation." (PMID 34698100, 2021). "Recently, NRP1 was found to modulate tumor-specific CD8+ T lymphocytes (LT CD8+) cell responses." (PMID 34277411, 2021). "In addition, the dual-targeting NP delivery system tLyP-1-HFt-PTX NPs was also developed which not only improved tumor penetration through an NRP-1–dependent internalization pathway but also bound to tumor cells by interacting with TfR1." (PMID 34675807, 2021). "Neuropilin-1 (NRP-1) and neuropilin-2 (NRP-2) act as co-receptors to members of the VEGF-receptor family and have been shown to play roles in vascular growth in developmental angiogenesis as well as tumor-associated angiogenesis." (PMID 35087885, 2021). "The role of NRP1 in the hypoxic tumor microenvironment in mediating VM has remained largely unknown." (PMID 33850110, 2021). "It seems that despite the well-defined knowledge of characteristics of VEGF, VEGFR, and NRP-1 molecular targets and the ability to proper radiotracer preparation, targeting and tumour imaging are still a challenge, due to heterogeneity and changeability of tumour environment." (PMID 33802353, 2021). "Although NRP1 is weakly expressed on Tregs isolated from human blood and cannot be used as an identifying marker for circulating human Tregs, it has recently been shown that in humans, NRP1 is expressed on CD4+ tumor-inflitrating lymphocytes (TILs), including Tregs." (PMID 34277411, 2021). "Anti-NRP1 antibody binding to pulmonary vasculature could alter vasculature structure, an event known to promote the outgrowth of disseminated tumor cells." (PMID 33128042, 2021).
tumor (continued). "Other RGD-containing peptides, such as iRGD (amino acid sequence: CRGDK/RGPD/EC), could also target cancer cells through binding to neuropilin-1 (NRP-1) receptors expressed in tumor and vascular tissues." (PMID 34993235, 2021). "Down-regulation of NRP1 by shRNA in ccRCC cells decreases migration, invasion and experimental human tumor growth, while NRP2 down-regulation results in decreased tumor cell extravasation in the lymphatic network and reduced cell metastatic dissemination in immunodeficient models." (PMID 33461580, 2021). "In this study, by comparing the expression of NRP1 in muscle invasive BC tissues to that in non-muscle invasive BC tissues, we found that increasing NRP1 was significantly associated with advanced tumor stage." (PMID 34249735, 2021). "In the present study, we showed the possibility that NRP-1 may be a key molecule in the enhancement of cell motility in radiation-surviving tumor cells." (PMID 34698100, 2021). "We further investigated the role of NRP1 in xenograft GC tumor model." (PMID 32508529, 2020). "C-terminal RLVR of PL3 corresponds to RXXR CendR consensus motif that, when exposed at the C-terminus, interacts with b1 domain of NRP-1 to trigger a trans-tissue pathway that mediates exit from the blood vessels and extravascular transport through tumor tissue." (PMID 32242067, 2020). "A main difference could be the lack of NRP-1 expression on the MC38 cancer cells, suggesting that the anti-tumor effect in this model is due to the blockade of NRP-1 on immune cells, of which myeloid cells showed the highest NRP-1 expression in MC38 tumors." (PMID 33266104, 2020). "Thus, tumor cell expression of NRP1 and more importantly, perivascular tumor cell expression, correlated with improved outcome in two independent RCC cohorts." (PMID 31880322, 2020). "Thus, neuropilin 1 suppression impacts on both tumor cells and the tumor microenvironment by down-regulating angiogenesis and extracellular matrix formation during the progression of metastasis." (PMID 32184727, 2020). "Thus, the primary targeting mechanism of H2K nanoplexes was likely neuropilin-1 (NRP1)-mediated transport through the tumor endothelium." (PMID 32823960, 2020). "Many cultured tumor cell lines overexpress NRP-1 and internalize peptides with active CendR motif." (PMID 32242067, 2020). "NRP1 may act as a substrate for the regulation of CRT/Smad3 pathway to induce EMT in NPC cells to promote tumor cell migration and invasion." (PMID 31956372, 2020). "NRP1 inhibition reduces tumor growth and a macrophages polarization to an anti-tumoral role." (PMID 32766254, 2020). "Importantly, NRP1-Δ7 acted anti-tumorigenic and diminished tumor vascularization in prostate cancer xenografts in vivo." (PMID 32984308, 2020). "Similarly, tumor regression has been observed only in melanoma-bearing mice treated with PD-1 targeted therapy together with antibodies against neuropilin-1." (PMID 33005420, 2020). "Notably, the expression of αv integrins is largely restricted in specific types of tumors, whereas that of NRP-1 is enhanced in many tumor types." (PMID 32847045, 2020). "Neutrophil elastase (NE) is also released by TANs and can be endocytosed by tumor cells via neuropilin-1 (NRP1); this results in the cross-presentation of PR1, which is an NE-derived HLA-A2-restricted peptide that may be an immunotherapeutic target." (PMID 32849640, 2020). "VEGF-A interacting with NRP1 could regulate Hippo signaling to drive tumor cell survival, angiogenesis, and tumor formation through facilitating the stabilization of YAP1." (PMID 32046779, 2020). "It was reported that NRP1 could play important role in tumor progression by promoting angiogenesis, proliferation, metastasis, and drug resistance in several different types of cancers." (PMID 32903845, 2020). "Seven studies assessed the relationship between NRP1 expression and tumor size." (PMID 33014187, 2020).
tumor (continued). "They proposed that the binding of iRGD with NRP-1 induces tyrosine phosphorylation of vascular endothelial cadherin, which subsequently opens cell contacts and allows lymphocytes to migrate to, and infiltrate the tumor parenchyma." (PMID 32847045, 2020). "Lower mRNA expression of SEMA3B, SEMA3D, SEMA3G, and PLXNA2 or higher mRNA expression of SEMA3F, NRP1, ITGB3, ITGA5, and VEGFA genes were detected in the older patient group and associated with the higher tumor grade, wild-type status of IDH, and lower rate of survival time (p < 0.05)." (PMID 33036421, 2020). "It remains to be determined whether there is a functional role of Nrp1 in maintaining BTSC stemness and tumor formation ability, as it is possible that Nrp1 inhibition of proliferation is indeed mechanistically linked to preventing differentiation." (PMID 33302912, 2020). "Neuropilin-1 (NRP1) appears crucial to maintain intratumoural Treg stability without aberrant loss of Foxp3 identity, and anti-NRP1 displayed therapeutic efficacy in suppressing tumor growth." (PMID 32849557, 2020). "In agreement with the in vitro results, immunoblotting analysis of tumor homogenates showed that shRNA-TTN-AS1 treatment led to downregulation of NRP-1, cyclin E, and CDK2, and upregulation of p27; while antagomiR-320a counteracted the effects of shRNA-TTN-AS1." (PMID 32801339, 2020). "A cancer cell xenograft model showed that NRP‐1 knockdown inhibited tumour progression in vivo." (PMID 32951327, 2020). "Moreover, IHC staining showed that knockdown of NRP1 notably down-regulated the expression of NRP1 and proliferation marker Ki-67 in tumor tissues." (PMID 32508529, 2020). "The expression of NRP1 was analyzed in different solid carcinomas including bladder, breast, colon, lung, ovarian and prostate and the up regulation of the biomolecule was correlated with advanced tumor stage and/or disease progression." (PMID 33002021, 2020). "Ingenuity pathway analysis demonstrated that NRP‐1 knockdown may inhibit tumour progression by affecting cell proliferation." (PMID 32951327, 2020). "High Nrp-1 levels were associated with VEGF overexpression and elevated MVD and, along with lower levels of semaphorins 3A and 3F (Sema 3A and 3F, proteins that can inhibit tumor angiogenesis when binding to Nrps), were associated with metastasizing cases." (PMID 33302367, 2020). "NRP1 is a multifunctional receptor interacting with a range of extracellular ligands, which might represent relevant triggers of NRP1-dependent tumor malignancy and molecular targets for restoring drug sensitivity." (PMID 32784465, 2020). "Furthermore, NRP1 expression showed positive correlation with tumor infiltration of Treg cells and M2 macrophages." (PMID 32408477, 2020). "Knockdown of NRP1 significantly repressed GC tumor growth in vivo." (PMID 32508529, 2020). "Another interesting observation is that NRP-1 deficiency in Tregs confers TH1 functions to these cells, including production of IFNγ, thereby influencing other Tregs and CD8+ T cells and stimulating anti-tumor immunity." (PMID 33266104, 2020). "In addition, NRP-1 expression has been described on various immune cells in the tumor microenvironment (TME), in particular on macrophages, dendritic cells (DCs) and regulatory T cells (Tregs)." (PMID 33266104, 2020). "In summary, knockdown of NRP1 suppresses GC tumor development and progression in vivo." (PMID 32508529, 2020). "Indeed, neuropilin-1 was detected in tumor cells of different cancer entities as well as in endothelial cells of the tumor vasculature." (PMID 32984308, 2020). "Thus, CD133-positive cells comprise a majority of the xenograft tumor and have elevated Nrp1 expression compared to CD133-negative/low cells." (PMID 33302912, 2020). "Among the tumor specimens with IDH mutation, mRNA levels of SEMA3B, SEMA3C, SEMA3D, SEMA3G, NRP2, PLXNA2, and CDH1 were significantly higher (p < 0.05), while SEMA3F, NRP1, ITGB3, ITGA5, and VEGFA genes were under-expressed (p < 0.05)." (PMID 33036421, 2020).
tumor (continued). "Neuropilin1 (NRP1) plays a critical role in tumor progression and immune responses." (PMID 32408477, 2020). "Recently, using a peptide-drug conjugate (ER-472) composed of ClTx linked to cryptophycin, it was demonstrated that the endocytic receptor on tumor and endothelial cells neuropilin-1 (NRP1) is a novel ClTx target which increases drug uptake leading to an enhanced antitumor activity." (PMID 32429050, 2020). "The pro-angiogenic activity of CgA1-373 requires the binding of its Pro-Gly-Pro-Leu-Arg373 site (PGPQLR373) to neuropilin-1: accordingly, antibodies against this site (which is cryptic in CgA1-439) can reduce angiogenesis and tumor growth in various animal models of solid tumors." (PMID 33425767, 2020). "Obviously, the link between NRP-1 expression on tumor-infiltrating immune cells and their tumor-promoting activity has instigated research in the development of NRP-1-blocking moieties, amongst others, monoclonal antibodies (mAbs) and tumor-penetrating peptides (TPPs)." (PMID 33266104, 2020). "In this study, we explored whether high prevalence of VEGFR2/NRP1 complexes or the expression of NRP1 by perivascular tumor cells impact RCC patient prognosis." (PMID 31880322, 2020). "Indeed, it has been shown that a natural occurring, soluble form of NRP1 can act as a VEGF165 antagonist exhibiting anti-tumor activity in vivo." (PMID 33121034, 2020). "Some evidence suggests that NRP-1 may present VEGF165 to VEGFR-2 to be involved in tumor angiogenesis in endothelial cells as a positive regulator of the VEGF signaling pathway." (PMID 33149867, 2020). "Genetically interrupting the migration of NRP-1-expressing TAMs to the hypoxic tumor core abrogates their acquisition of pro-tumor functions, instead allowing the induction of anti-tumor T helper 1 (TH1) and cytotoxic T lymphocyte (CTL) responses and a reduction of tumor progression." (PMID 33266104, 2020). "Treg-specific Nrp1 deletion has been shown to significantly dampen tumor growth." (PMID 33344447, 2020). "Expression of NRP-1 was detected in normal mammary ducts and in the tumor cells." (PMID 31812165, 2019). "Concomitant blockade of Nrp-1 and PD-1 could remedy this cold-tumour situation, thus providing an immunotherapeutic strategy for further improving specific immune responses during cancer disease." (PMID 31350404, 2019). "However, little is known about the mechanisms of NRP1-induced tumor cell radiation resistance in the microenvironment at different stages of the tumor." (PMID 31417646, 2019). "As we hypothesized, NRP1 played critical roles in tumor growth and cell radiation resistance, respectively." (PMID 31417646, 2019). "Thus, the migration ability of tumor cells was closely related to NRP1 expression in the tumor microenvironment." (PMID 31417646, 2019). "Therefore, we further explored the role of NRP1 in the tumor inflammatory microenvironment produced under 3D co-culture conditions." (PMID 31417646, 2019). "Several therapeutic anticancer therapies focus on inhibition of Nrp1 to restrict tumor growth, and so knowledge of how Nrp1 blockade may affect the CD8 T cell response will provide a better understanding of treatment consequences." (PMID 31118303, 2019). "Indeed, several studies have shown that targeting either NRP1 or NRP2 can inhibit tumor initiation and decrease resistance to other therapies." (PMID 30678134, 2019). "We expect that the xMAP‐based assay of Nrp1 and Nrp2 could be clinically applied in early‐stage cancer screening, tumor malignancy analysis, and patient prognosis assessment." (PMID 30758083, 2019). "A monoclonal antibody against NRP1 inhibits EC migration and tumorigenesis in mouse tumor models." (PMID 30717262, 2019). "In addition, pre-treatment with an antibody to block tumor-expressed NRP1 reduced the potency of ER-472 in PC-3 tumors." (PMID 31208428, 2019). "Due to the expression of NRP-1 in U87 tumor cells, this targeting strategy may potentiate tumor cell and molVTP in vivo." (PMID 33568892, 2019).
tumor (continued). "We then focused on induction of Nrp-1 on CD8+ TIL during tumour progression." (PMID 31350404, 2019). "Notably, patients with low tumor expression of NRP1 showed a better overall survival rate compared to patients with high NRP1 expression." (PMID 31027288, 2019). "After binding to p32 (GClqR), which is expressed on peritoneal caricnoma cells of gastric, ovarian and colon origin in mouse models as well as clinical peritoneal carcinoma explants, cleavage by uPA exposes their NRP1 targeting CendR motif which mediates vascular exit and tumor penetration." (PMID 30717262, 2019). "Notably, a combination of anti-Nrp-1 plus anti-PD-1 did not further increase target cell killing, suggesting that cytotoxicity is mainly mediated by the Nrp-1+PD-1hi TIL subset that includes most tumour-specific effector T cells." (PMID 31350404, 2019). "The seven class 3 semaphorins, SEMA3A-G, are secreted members of a large family of guidance factors that regulate processes, such as developmental and tumor angiogenesis, by signaling through receptors composed of NRP1 or NRP2 and plexinA or plexinD, respectively." (PMID 30717262, 2019). "NRP1 is overexpressed by angiogenic ECs of the tumor vasculature and in diverse tumor cells." (PMID 30717262, 2019). "Moreover, NRP-1 expression correlates with tumor progression and poor prognosis in various cancers, including PDAC27." (PMID 31754378, 2019). "Importantly, a combination of anti-Nrp-1 plus anti-PD-1 was clearly additive, with a much better control of tumour progression." (PMID 31350404, 2019). "Interestingly, NRP1 is well expressed on TAMs and it is critical for their migration to the hypoxic core of the tumor, where they release proangiogenic and immunosuppressive factors." (PMID 31027288, 2019). "Likewise, we found, in B16F10 tumours, that a significant percentage of Nrp-1+PD-1hi CD8+ TIL strongly expressed granzyme B and cell proliferation marker Ki-67, and secreted high levels of IFNγ." (PMID 31350404, 2019). "In addition, different expression levels of NRP1 in 2D, 3D culture systems and tumor-bearing models were able to significantly regulate cell phenotype, proliferative capacity, epithelial-mesenchymal transition (EMT) and the radiation resistance of A549 cells." (PMID 31417646, 2019). "Blocking NRP1 signaling reduces tumor angiogenesis and tumor growth." (PMID 31652529, 2019). "SEMA3C exerts its inhibitory effect especially on ECs in immature vessel sprouts, as these markedly express NRP1 and PlexinD1; thus, specific plexin D1 ligands may be useful to inhibit tumor angiogenesis." (PMID 30717262, 2019). "NRP1, a well-described receptor for vascular endothelial growth factor (VEGF) and semaphorins, has been implicated to be involved in various biological processes including angiogenesis, neuronal development, cell survival, migration, and tumor-invasion." (PMID 31572401, 2019). "Notably, wild-type KRAS is found in tumors where NRP1 has tumor-promoting properties, while in tumors where NRP1 acts as a tumor suppressor, oncogenic KRAS mutations are found." (PMID 30717262, 2019). "Semaphorin 3A (Sema3A), a physiological ligand of Nrp1 (23, –, 25), inhibits in vitro dendritic cell (DC)-T cell interactions and tumor-T cell interactions, and by blocking Sema3A, hence suppressing the downstream signaling involving Nrp1, T cell activation and proliferation were restored." (PMID 31118303, 2019). "Caco-2 cells also express NRP1, which is a non-tyrosine kinase receptor associated with tumor migration and survival." (PMID 31426807, 2019). "However, 2 of the tumor patient serum samples (30# and 31#) showed significantly higher concentrations of NRP1 and NRP2 than those of normal human serum." (PMID 30758083, 2019). "Overexpression of NRP1 in tumor cells has also been shown to enhance tumor angiogenesis." (PMID 31723119, 2019).